KAT7 (lysine acetyltransferase 7)
Description:
Catalytic subunit of histone acetyltransferase HBO1 complexes, which specifically mediate acetylation of histone H3 at 'Lys-14' (H3K14ac), thereby regulating various processes, such as gene transcription, protein ubiquitination, immune regulation, stem cell pluripotent and self-renewal maintenance and embryonic development. Some complexes also catalyze acetylation of histone H4 at 'Lys-5', 'Lys-8' and 'Lys-12' (H4K5ac, H4K8ac and H4K12ac, respectively), regulating DNA replication initiation, regulating DNA replication initiation. Specificity of the HBO1 complexes is determined by the scaffold subunit: complexes containing BRPF scaffold (BRPF1, BRD1/BRPF2 or BRPF3) direct KAT7/HBO1 specificity towards H3K14ac, while complexes containing JADE (JADE1, JADE2 and JADE3) scaffold direct KAT7/HBO1 specificity towards histone H4. H3K14ac promotes transcriptional elongation by facilitating the processivity of RNA polymerase II. Acts as a key regulator of hematopoiesis by forming a complex with BRD1/BRPF2, directing KAT7/HBO1 specificity towards H3K14ac and promoting erythroid differentiation. H3K14ac is also required for T-cell development (By similarity). KAT7/HBO1-mediated acetylation facilitates two consecutive steps, licensing and activation, in DNA replication initiation: H3K14ac facilitates the activation of replication origins, and histone H4 acetylation (H4K5ac, H4K8ac and H4K12ac) facilitates chromatin loading of MCM complexes, promoting DNA replication licensing. Acts as a positive regulator of centromeric CENPA assembly: recruited to centromeres and mediates histone acetylation, thereby preventing centromere inactivation mediated by SUV39H1, possibly by increasing histone turnover/exchange. Involved in nucleotide excision repair: phosphorylation by ATR in response to ultraviolet irradiation promotes its localization to DNA damage sites, where it mediates histone acetylation to facilitate recruitment of XPC at the damaged DNA sites. Acts as an inhibitor of NF-kappa-B independently of its histone acetyltransferase activity. Plays a central role in the maintenance of leukemia stem cells in acute myeloid leukemia (AML). Acts by mediating acetylation of histone H3 at 'Lys-14' (H3K14ac), thereby facilitating the processivity of RNA polymerase II to maintain the high expression of key genes, such as HOXA9 and HOXA10 that help to sustain the functional properties of leukemia stem cells.
Synonyms: HBO1; HBOa; MYST2; ZC2HC7
Tractability: Small molecule: a structure with a bound ligand is known. PROTAC: UniProt records ubiquitination sites on it; ubiquitination databases record sites on it; its protein half-life has been measured; a small molecule that binds it is known.
Target class: Enzyme
Chemical probes: WM-3835 (high quality)
Gene: Protein-coding gene on chromosome 17 (49,788,624 to 49,835,026, forward strand). Ensembl gene ENSG00000136504.
Subcellular location: Nucleus; Chromosome; Chromosome, centromere; Cytoplasm, cytosol
Subcellular location (Human Protein Atlas): Nucleoplasm; Cytosol
Pathways (Reactome):
Chromatin organization: HATs acetylate histones
Gene Ontology:
Molecular function: DNA replication origin binding; histone acetyltransferase activity; histone H3K14 acetyltransferase activity; histone H3K23 acetyltransferase activity; histone H3K4 acetyltransferase activity; histone H4 acetyltransferase activity; histone H4K12 acetyltransferase activity; histone H4K16 acetyltransferase activity; histone H4K5 acetyltransferase activity; histone H4K8 acetyltransferase activity; protein binding; chromatin binding; histone H3 acetyltransferase activity; transcription coregulator activity; protein-lysine-acetyltransferase activity; zinc ion binding
Biological process: DNA replication-dependent chromatin disassembly; internal peptidyl-lysine acetylation; positive regulation of DNA replication; positive regulation of hematopoietic stem cell proliferation; positive regulation of protein localization to nucleus; regulation of cell cycle; regulation of cell growth; regulation of DNA biosynthetic process; regulation of DNA replication; regulation of DNA-templated DNA replication initiation; regulation of DNA-templated transcription; regulation of nucleotide-excision repair; response to actinomycin D; response to anisomycin; response to dithiothreitol; response to hydroxyurea; response to sorbitol; stress-activated protein kinase signaling cascade; transcription initiation-coupled chromatin remodeling; natural killer cell differentiation; positive regulation of DNA-templated transcription, elongation; regulation of transcription by RNA polymerase II; positive regulation of erythrocyte differentiation; positive regulation of transcription by RNA polymerase II; T cell differentiation
Cellular component: chromosome; histone acetyltransferase complex; histone H3-K14 acetyltransferase complex; nucleolus; nucleoplasm; nucleus; site of DNA damage; chromosome, centromeric region; cytosol
Genetic constraint (gnomAD): Loss-of-function variants: 7 observed, 47.8 expected, observed/expected ratio (o/e) 0.15, 90% interval 0.082 to 0.28. The upper end of that interval is the gene's LOEUF score, 0.28, which puts it in group 1 of 6, group 1 being the genes least tolerant of losing a copy. Missense variants: 262 observed, 542.12 expected, observed/expected ratio (o/e) 0.48, 90% interval 0.44 to 0.54. Synonymous variants: 176 observed, 186.95 expected, observed/expected ratio (o/e) 0.94, 90% interval 0.83 to 1.07.
Homologues: Orthologues: chimpanzee KAT7 (100% identical), dog KAT7 (100% identical), macaque KAT7 (99% identical), mouse Kat7 (99% identical), rat Kat7 (99% identical), rabbit KAT7 (99% identical), guinea pig KAT7 (99% identical), tropical clawed frog kat7 (95% identical), pig KAT7 (94% identical), zebrafish kat7b (78% identical), Caenorhabditis elegans lsy-12 (35% identical). Paralogues in human: KAT6B (40% identical), KAT6A (40% identical), KAT5 (30% identical), KAT8 (29% identical), RSF1 (17% identical), DPF3 (11% identical), DPF1 (11% identical), DPF2 (10% identical), PHF10 (10% identical).
Diseases named in the same sentence as KAT7 in open-access papers:
KAT7 is named in the same sentence as 59 diseases in open-access papers, as found by Europe PMC text mining. Sharing a sentence is not in itself a finding about the gene and the disease. The quoted sentences say what the papers report.
leukemia (17 papers, 2020 to 2025). A malignant (clonal) hematologic disorder, involving hematopoietic stem cells and characterized by the presence of primitive or atypical myeloid or lymphoid cells in the bone marrow and the blood. "KAT7 has been implicated as a dependency in MLL-rearranged leukemia with inhibition of enzymatic activity as the therapeutic focus." (PMID 36707513, 2023). "KAT7 dysregulation is associated with a variety of cancers and, similar to KAT6A, KAT7 chromosomal translocations cause leukaemia." (PMID 37275850, 2023). "Knocking out KAT7 reduces the viability and proliferation of leukemia cells and induces cell apoptosis." (PMID 40612663, 2025). "Some studies have suggested that KAT7 plays a critical role in the survival of leukemia cells 21,24,28." (PMID 39816686, 2025). "Both KAT6A and KAT7 are promising targets for anti-cancer therapy, in particular leukaemia, and a drug inhibiting the enzymatic activity of KAT6A is in clinical trials." (PMID 37275850, 2023). "In another leukemia study, KAT7, an acetyltransferase that deposits acetyl moiety on lysine 14 and lysine 23 of histone H3, was identified as a critical target in leukemic cells harboring MLL-fusion proteins but not in leukemic cells with wild-type MLL." (PMID 36401282, 2022). "KAT7 KO increased apoptosis in MLL-r leukemia cells, providing a breakthrough in novel target discovery based on the genetic makeup of hematological malignancies." (PMID 36401282, 2022). "CRISPR/Cas9-mediated sgRNA competition assays demonstrated that Kat7/KAT7 (the gene encoding HBO1) is required for the proliferation of various MLL fusion-ICs and in human leukemia cell lines." (PMID 34431785, 2021). "Notably, the KAT gene is necessary for the maintenance of leukemia tumor stem cells, and knocking out KAT7 attenuated leukemia." (PMID 39161800, 2024). "Notably, the MYST acetyltransferase HBO1 (also known as KAT7 or MYST2) and several members of the HBO1 protein complex, which were recently shown as critical regulators of leukemia stem cell maintenance, were also identified among the top hits." (PMID 33001025, 2020). "For instance, WM-3835 can chemically inhibit the acetyl-CoA binding site of HBO1 (KAT7 or MYST2), ultimately inhibiting leukemia stem cell growth." (PMID 37394580, 2023). "Low expression of KAT7 (MYST2) rapidly determines a lack of H3K14 and H4K12 acetylation, slowing cell growth and inducing apoptosis and differentiation of leukaemia cells." (PMID 36539894, 2022).
breast carcinoma (16 papers, 2010 to 2025). "Consistently, a previous study reported that KAT7 promotes destabilization of estrogen receptor α through lysine 48-linked ubiquitination to induce breast cancer cell proliferation." (PMID 36724120, 2023). "The level of KAT7 is associated with clinical outcomes in cancer patients, suggesting its value with clinical prognosis, histological grading and therapeutic targets in breast cancer." (PMID 36724120, 2023). "This evidence highlights the oncogenic role of KAT7 in enhancing breast cancer radioresistance through transcriptional upregulation of PIK3CA and PI3K/AKT pathway activation, suggesting therapeutic potential in KAT7 inhibition." (PMID 40740483, 2025). "Recent studies in human breast cancer have shown that KAT7 upregulates phosphoinositide 3-kinase (PIK3CA), leading to activation of the PI3K/AKT signaling pathway, which is known to contribute to cell survival and proliferation." (PMID 41168812, 2025). "KAT7 has recently been reported to function as a novel cyclin E/CDK2 substrate that enriches stem-like cells in breast cancer." (PMID 36724120, 2023). "Taken together, these results provided compelling evidence that KAT7 promoted radioresistance in breast cancer." (PMID 36724120, 2023). "In conclusion, KAT7 activates PI3K/AKT signaling to regulate radioresistance by upregulating PIK3CA expression in breast cancer." (PMID 36724120, 2023). "Except breast cancer, KAT7 was reported to function as an oncogene in other cancers, including gastric cancer, acute myeloid leukemias, bladder cancer and ovarian cancer." (PMID 36724120, 2023). "KAT7 enhances growth of breast cancer cells and knockdown of the KAT7 gene impairs cell proliferation, which suggests that KAT7 function as an oncogene." (PMID 36724120, 2023). "KAT7 expression negatively correlated with the survival of breast cancer patients, and KAT7 silencing suppressed breast cancer radioresistance in vitro." (PMID 36724120, 2023). "Herein, we reported a hitherto undocumented relationship between KAT7 expression in breast cancer and its relationship with survival." (PMID 36724120, 2023). "KAT7 knockdown significantly inhibited AKT phosphorylation at Ser473 site, which indicated that KAT7 regulates AKT activity in breast cancer." (PMID 36724120, 2023). "Phosphorylation of downstream KAT7 by the LMW-E/CDK2 complex enhances the self-renewal ability of breast cancer cells and the enrichment of cancer stem cells populations." (PMID 36724120, 2023). "In a nutshell, our results corroborated that KAT7 has significant value as a novel molecular target for treating breast cancer." (PMID 36724120, 2023). "The new roles of KAT7 in breast cancer radioresistance contribute to a better understanding of KAT7 functions and regulation in cancer." (PMID 36724120, 2023). "In conclusion, KAT7 has huge prospects for clinical application as a new target for predicting radioresistance in breast cancer patients." (PMID 36724120, 2023). "To detect the role of KAT7 in breast cancer radioresistance, we first suppressed KAT7 protein and mRNA expression using shRNAs." (PMID 36724120, 2023). "Given that the AKT signaling pathway is critical for radioresistance in breast cancer, we first analyzed the effect of KAT7 suppression on AKT phosphorylation in breast cancer cells." (PMID 36724120, 2023). "The cyclin E/CDK2 complex phosphorylates KAT7 at Thr88 which promotes the enrichment of breast cancer stem-like cells." (PMID 33014433, 2020). "KAT7 enhances radioresistance in breast cancer by increasing PI3K/AKT." (PMID 40740483, 2025). "Moreover, silencing of KAT7 has been shown to suppress breast cancer radioresistance in vitro, highlighting its importance in radiation response." (PMID 41369374, 2025). "Elevated levels of KAT7 in breast cancer patients have a detrimental effect on survival rates." (PMID 40740483, 2025).
breast carcinoma (continued). "Based on these findings, combining targeted therapy against KAT7 with inhibition of the PI3K pathway may offer a promising approach for improving breast cancer treatment." (PMID 41168812, 2025). "However, the function and mechanism of KAT7 in breast cancer radioresistance remain largely understudied." (PMID 36724120, 2023). "KAT7 is a potential prognostic marker and therapy target for breast cancer." (PMID 36724120, 2023). "Suppression of KAT7 by shRNAs inhibited breast cancer radioresistance." (PMID 36724120, 2023). "Nonetheless, the mechanisms by which KAT7 regulates oncogenesis and radioresistance in breast cancer remain unclear, warranting further investigation." (PMID 36724120, 2023). "Our results revealed that KAT7 acts as an oncogene in breast cancer radioresistance." (PMID 36724120, 2023). "Herein, we demonstrated that Lysine acetyltransferase 7 (KAT7) was upregulated in breast cancer." (PMID 36724120, 2023). "Overall, these findings demonstrated that KAT7 regulates PIK3CA expression in breast cancer." (PMID 36724120, 2023). "Finally, we assessed the molecular mechanisms by which KAT7 mediates breast cancer radioresistance." (PMID 36724120, 2023). "KAT7 overexpression enhances the phosphoinositide 3-kinase (PI3K)/protein kinase B (Akt) signaling pathway, which is frequently dysregulated in breast cancer, promoting tumor growth, survival, and metabolism, and also contributes to radioresistance." (PMID 41369374, 2025). "In multiple breast cancer cell lines, upregulation of lysine acetyltransferase 7 (KAT7) has been reported, and its expression was negatively correlated with the survival of breast cancer patients." (PMID 41369374, 2025). "Our results demonstrate that KAT7 knockdown inhibited breast cancer radioresistance through PI3K/AKT signaling and PIK3CA or Mry-AKT overexpression rescued KAT7 inhibition-suppressed cell radioresistance." (PMID 36724120, 2023). "Herein, we revealed that KAT7 upregulates PIK3CA, leading to activation of the PI3K/AKT signaling pathway, thus promoting radioresistance in breast cancer." (PMID 36724120, 2023). "To uncover if KAT7 is essential for breast cancer progression, we first analyzed alterations in the mRNA levels of the KAT family in breast cancer patients." (PMID 36724120, 2023). "The present study found that KAT7 expression is upregulated in breast cancer compared with normal tissue." (PMID 36724120, 2023). "Furthermore, we found a negative correlation between KAT7 expression and survival of breast cancer patients." (PMID 36724120, 2023).
gastric cancer (10 papers, 2020 to 2025). A primary or metastatic malignant neoplasm involving the stomach. "Over the years, KAT7 aberrant expression has been associated with oncogenesis in gastric cancer, acute myeloid leukemias, bladder cancer and ovarian cancer." (PMID 36724120, 2023). "Our findings not only reveal the pivotal roles of circMRPS35 in governing histone modification in anticancer treatment, but also advocate for triggering circMRPS35/KAT7/FOXO1/3a pathway to combat gastric cancer." (PMID 32164722, 2020). "KAT7 is up-regulated in a variety of cancers such as breast, prostate, bladder and gastric cancer." (PMID 37365518, 2023). "In conclusion, our study demonstrates that circMRPS35 recruits histone acetyltransferase KAT7 as a modular scaffold, which subsequently increases the level of H4K5ac in the promoter regions of FOXO1 and FOXO3a and ultimately suppresses the proliferation and invasion of gastric cancer cells." (PMID 32164722, 2020).
osteosarcoma (9 papers, 2021 to 2025). A usually aggressive malignant bone-forming mesenchymal neoplasm, predominantly affecting adolescents and young adults. "WM-3835 is a potent and highly specific HBO1 (KAT7 or MYST2) inhibitor that directly binds to the acetyl-CoA binding site of HBO1 33 WM-3835 activates apoptosis while inhibiting osteosarcoma (OS) cells proliferation, migration and invasion." (PMID 36171897, 2022). "Additionally, another study revealed the overexpression of KAT7 in osteosarcoma, where it functions as a newly identified oncogenic gene crucial for tumor development and progression." (PMID 39816686, 2025).
hepatocellular carcinoma (8 papers, 2021 to 2024). A malignant tumor that arises from hepatocytes. "Bai found that miR-639 inhibits the proliferation and migration of human hepatocellular carcinoma cells through the KAT7/Wnt/β-Catenin Pathway, KAT7 expression promotes cell proliferation and migration of human HCC cells in vitro." (PMID 36575369, 2022).
colorectal cancer (7 papers, 2019 to 2025). A primary or metastatic malignant neoplasm that affects the colon or rectum. "A significant elevation of KAT7 expression in colorectal cancer compared to adjacent normal tissues was also demonstrated by immunohistochemical analysis." (PMID 39816686, 2025). "The enzymatic function of KAT7 as an acetyltransferase is crucial for the advancement of colorectal cancer." (PMID 39816686, 2025). "Overall, our findings suggest that overexpression of KAT7 has the potential to accelerate the progression of colorectal cancer in vitro." (PMID 39816686, 2025). "For example, lncRNA ENO1-it1 regulating glycolysis through KAT7 to promote malignant transformation of colorectal cancer." (PMID 38519939, 2024). "Conversely, lncRNA KAT7 is significantly downregulated in colorectal cancer (CRC) tissues, and overexpression of KAT7 can inhibit malignant behavior in CRC." (PMID 35526240, 2022). "For instance, lncRNA ENO1-IT1 functioned as a molecular guide for lysine acetyltransferase 7 (KAT7) histone acetyltransferase, dictating the histone modification pattern on its target genes, such as enolase 1 (ENO1), and thereby modulating glycolysis in colorectal cancer (CRC)." (PMID 40722703, 2025).
ovarian carcinoma (5 papers, 2021 to 2023). A malignant neoplasm originating from the surface ovarian epithelium. "We ultimately constructed a histone acetylation modulator-related signature containing 10 histone acetylation modulators, among which HDAC1, HDAC10, and KAT7 can act as independent prognostic factors for ovarian cancer and are related to poor prognosis." (PMID 36172179, 2022). "Studies have shown that KAT7 enhances the mechanical transduction pathway and membrane elasticity of ovarian cancer cells through the overexpression of preferential acetylation histone H4 of co-mediator JADE2, thus improving the migration ability and invasiveness of ovarian cancer cells." (PMID 36172179, 2022).
Alzheimer disease (2 papers, 2022 to 2026). A progressive, neurodegenerative disease characterized by loss of function and death of nerve cells in several areas of the brain leading to loss of cognitive function such as memory and language. "KAT7 (MYST2) has effects on β-catenin or the Wnt inhibitor Dkk1 in Alzheimer's disease positively regulating tau phosphorylation and exacerbating cognitive deficits." (PMID 36539894, 2022).